BRAF (B-Raf proto-oncogene, serine/threonine kinase)
Diseases named in the same sentence as BRAF in open-access papers (continued):
Sharing a sentence is not in itself a finding about the gene and the disease.
tumor (continued). "The allele frequency (AF), representing the proportion of mutated DNA within a sample, has been correlated with tumor behavior in certain mutations, such as BRAF V600E." (PMID 40940948, 2025). "Around 90% of MA cases have been linked to the BRAF V600E mutation, providing further insight into the molecular mechanisms underlying the tumor." (PMID 40248024, 2025). "The phase II Circulating Tumor DNA Guided Switch (CAcTUS) trial (NCT03808441) focuses on MM patients with BRAF V600 mutations." (PMID 39859576, 2025). "After identifying specific genetic mutations in the tumor, it is possible to tailor systemic therapy using drugs that target these mutations, such as BRAF, MEK, KIT inhibitors, or checkpoint inhibitors." (PMID 40344340, 2025). "MITF, Ki67, BRAF, and PD-L1 are associated with prognosis factors, like the Breslow thickness, tumour ulceration, type of inflammatory infiltrate, and response to treatment." (PMID 40507250, 2025). "In this study, the impact of tovorafenib alone or in combination with MEK inhibitor, pimasertib, was explored in adult or pediatric tumor models harboring BRAF fusions or NF1-LOF mutations." (PMID 40111124, 2025). "Patients with intrahepatic BTC harboring BRAF V600E mutations often present with advanced tumor stages at surgery, increased lymph node involvement, and generally poorer outcomes compared to patients without these mutations." (PMID 40332392, 2025). "There is also a distinctive histopathological correlation: tumor cells carrying the BRAF p.Val600Glu (V600E) mutation often exhibit markedly enlarged, pleomorphic nuclei." (PMID 41473634, 2025). "Recent findings indicate that CXCL8 production by cancer cells in vitro is regulated at multiple levels and is strongly influenced by the tumor’s genetic profile, particularly mutations in genes such as BRAF and Phosphatase and Tensin Homolog (PTEN)." (PMID 40943634, 2025). "The hyperactivity of cancer-associated fibroblasts (CAFs) and tumor-associated macrophages (TAMs) appear to promote resistance of neoplastic cells to bRAF inhibitors." (PMID 40507830, 2025). "While later stage tumors had a greater frequency of BRAF p.V600E mutations than stage 1 tumors did, the association between BRAF p.V600E mutations and survival persisted with stage adjustment and was evident across case groups defined by tumor site and sex." (PMID 41413856, 2025). "Group 1 tumours contain more BRAF V600E mutations and present with seizures at a median of 30.2 months." (PMID 40013208, 2025). "In recent years, breakthroughs have been made in understanding the molecular biology of PCP, particularly regarding the BRAF V600E mutation, leading to significant advances in targeted therapies and affirming its status as a distinct tumor entity." (PMID 40696244, 2025). "Subsequently, these patients were categorized into four groups based on both BRAF mutational status and intra-tumor TLS (BRAFWTTLSHigh, BRAFWTTLSLow, BRAFMTTLSHigh, and BRAFMTTLSLow)." (PMID 40959083, 2025). "By inhibiting key molecules involved in critical signaling pathways, such as the HER2 receptor in breast cancer or the BRAF protein in melanoma, targeted therapies can effectively suppress tumor growth and reduce the risk of relapse." (PMID 39934876, 2025). "The pattern of KRAS and BRAF mutations across different tumor sites (colon vs. rectum) was significantly associated with KRAS mutation (p=0.03)." (PMID 40949797, 2025). "Molecular analysis showed that the tumor tissue, composed solely of rhabdoid cells, also harbored a BRAF V600E mutation and homozygous CDKN2A deletion, molecular signatures of PXA, along with loss of INI1 expression." (PMID 40231261, 2025). "In the EP group, 12 tumours had pathogenic mutations in key genes associated with response to anti‐EGFR therapy (1 × in BRAF + PTEN, 1 × in BRAF + PIK3CA, 2 × in BRAF, 3 × in PTEN, 2 × in NRAS, 1 × in KRAS, 1 × in HRAS and 1 × in PIK3CA)." (PMID 40302146, 2025).
tumor (continued). "Three months after the treatment, skin metastasis appeared, so DTIC was discontinued, and he began treatment with vemurafenib because his tumor was positive for BRAF mutations." (PMID 40416034, 2025). "18F-FDG PET/CT is widely used for the evaluation of radioiodine-refractory DTC, particularly in cases with aggressive tumor mutations like BRAF V600E." (PMID 39941793, 2025). "A higher risk of lymph node metastasis is also characteristic of patients with tumor invasion into lymphatic vessel lumens and those with the BRAF V600E mutation in tumor tissue." (PMID 41141346, 2025). "Combination treatment with oHSV and Trametinib enhanced virus replication mediated by down-regulation of STAT1 and PKR expression or phosphorylation in BRAF V600E-mutated tumor cells as well as BRAF wt/KRAS-mutated tumor cells." (PMID 40248194, 2025). "Differences in the content of adjacent lymph nodes and the tumor-derived connective tissue between the BRAF V600 mortality-risk groups and among the proteomic subtypes pointed to a link between the TME and patient outcome." (PMID 40075679, 2025). "As the frequency of BRAF p.V600E mutations differed significantly by tumor and patient characteristics, we further stratified DS-survival analyses by both tumor site and sex." (PMID 41413856, 2025). "when combined oHSV with PD-1 blockade and MEK inhibition, they found a remarkably synergistic therapeutic efficacy in vivo for BRAF wt/KRAS-mutated tumor models." (PMID 40248194, 2025). "Tovorafenib selectively inhibits tumor growth associated with both BRAF fusions and V600 mutations while demonstrating favorable brain penetrability." (PMID 40430547, 2025). "In targeted therapy, nanoparticles carrying tyrosine kinase inhibitors (TKIs, such as icotinib or erlotinib) can specifically inhibit signaling pathways driven by EGFR or BRAF mutations, while simultaneously sensitizing tumor cells to ferroptosis inducers." (PMID 40416987, 2025). "The significant associations between KRAS and BRAF mutations with tumor differentiation, grade, and metastatic patterns highlight their prognostic relevance." (PMID 40949797, 2025). "Right colon primary tumours were associated with BRAF-V600Emt and dMMR and had worse median overall survival (mOS) than left colon or rectal mCRC." (PMID 40437037, 2025). "Other predictive markers include mutations in KRAS/NRAS and BRAF V600E, tumor mutational burden, and imaging-based radiomic parameters such as metabolic tumor volume (MTV) and total lesion glycolysis on PET/CT." (PMID 41002551, 2025). "The literature data from the recent decade highlight the roles of tumour-associated mast cells, microRNAs (miRNAs), and BRAF, alongside KRAS genes, in CRC initiation and progression." (PMID 39996841, 2025). "Multivariate logistic regression determined the association between BRAF testing with patient/tumour characteristics and BRAF genotype with patient/tumour characteristics." (PMID 40902091, 2025). "The clinical information of the patients from whom the samples were derived varied, including factors such as age, sex, tumor (benign or malignant) infiltration depth, and BRAF and NRAS mutation status." (PMID 40098976, 2025). "When mutation- and MMR-status for primary tumour location were analysed beyond the trichotomous division, BRAF-V600Emt were more common from caecum to descending colon compared with sigmoid colon to rectum (27–48% vs 5–6%, p < 0.001)." (PMID 40437037, 2025). "In summary, tumor localization, BRAF mutation status, ‘de novo’ metastasis/recurrence disease, MCS, and subsequent IO seem to have prognostic value in univariate analysis (p: 0.036, p < 0.01, p: 0.04, p: 0.03, and p: 0.005, respectively)." (PMID 41294701, 2025).
tumor (continued). "In sporadic CRC, MSI has been strongly associated with BRAF mutations (v-raf murine sarcoma viral oncogene homolog B1), older age, right-sided tumor localization, and high levels of the CpG island methylator phenotype (CIMP)." (PMID 40142201, 2025). "The research showed that patients with one type of BRAF mutation (called V600) tended to be older, have tumours on the right side of the bowel, and were more likely to see the cancer return quickly after treatment." (PMID 41002577, 2025). "This study aimed to illuminate the association between physical activity and the risk of CRC by tumor molecular subtypes (microsatellite instability, CpG island methylator phenotype, BRAF, and KRAS mutation status)." (PMID 41031512, 2025). "In PCPs with confirmed BRAF V600E mutation, BRAF-targeted therapy can be used as neoadjuvant therapy to shrink tumor size." (PMID 40444237, 2025). "Higher serum TNF levels were associated with female sex (P = 0.026), older age (P < 0.001), BRAF mutation (P = 0.030), less frequent lymphovascular invasion (P = 0.044), and proximal tumor location (P < 0.001)." (PMID 40928327, 2025). "We also used Sanger sequencing to detect six genes—KRAS, NRAS, HRAS, TERT, RET, and BRAF—in the tumor tissue and identified a C228T mutation in the TERT promoter region." (PMID 41488090, 2025). "Patients with BRAF V600K mutations had similar levels of baseline tumor CD8 T cell infiltration to patients with BRAF V600E mutations." (PMID 40993242, 2025). "In CRC, aberrant MAPK signaling is frequently driven by oncogenic mutations in RAS and BRAF, leading to uncontrolled tumor growth, resistance to apoptosis, and metastasis." (PMID 40227607, 2025). "MicroRNAs (miRNAs) are main epigenetic modulators showing dysregulation in association with BRAF/MEKi resistance and with tumor-induced immune dysfunctions." (PMID 41550951, 2025). "For example, the increased levels of HMOX1 have been associated to tumor aggressiveness and presence of serine/threonine-protein kinase B-Raf (BRAF)V600E mutation." (PMID 40927570, 2025). "The molecular basis of CPs has been elucidated with over 95% of pCP harbouring the BRAF c.1799T > A, p.(Val600Glu) variant commonly referred to as ‘V600E’, and this variant has recently been targeted with BRAF-MEK inhibitors with profound tumour shrinkage." (PMID 39900703, 2025). "On the other hand, the detection of pathogenic variants in ctDNA was notably inconsistent compared to those identified in tumor tissue, particularly with respect to BRAF gene mutations." (PMID 40725233, 2025). "Emerging evidence suggests BRAF mutation status requires integration with tumor microenvironment biomarkers (e.g. PD-L1 expression) for precise therapeutic prediction." (PMID 40969790, 2025). "In this study, BRAF status and proximal tumor location associated with both high TIMP1 serum levels and TIMP1 expression in tumor tissue." (PMID 39789100, 2025). "The impact of the BRAF V600E mutation on tumor microenvironment characteristics, gene expression, and signaling pathways was evaluated using bioinformatics approaches." (PMID 39934467, 2025). "Tumours with BRAF V600E mutations have also shown greater susceptibility to MEK inhibition compared to wild-type BRAF cells, providing a rationale for combination therapy." (PMID 39671021, 2025). "PCR analyses of the first tumor revealed a BRAF V600E mutation, and fluorescence in situ hybridization demonstrated homozygous CDKN2A deletion in both components." (PMID 40231261, 2025). "This variability in CD44v6 expression probably reflects differences in tumor biology and underlying molecular mechanisms, with lower expression observed in tumors harboring BRAF mutations." (PMID 41039489, 2025). "Here, we performed a comprehensive molecular characterization of MSS BRAF V600E CRCs to study the link between BRAF mutations, tumor metabolism and DNA methylation." (PMID 40102611, 2025).
tumor (continued). "This development was evident in the TransMet trial, where patients with BRAF tumour mutation were excluded due to its associated poor prognosis." (PMID 40108728, 2025). "“Oncological resectability” emphasizes achieving durable disease control, integrating factors such as tumor biology (RAS/BRAF mutation status, response to systemic therapy) and patient’s general condition into surgical decision-making." (PMID 40805233, 2025). "The BRAF V600E mutation is commonly associated with tumour recurrence, independently of conventional clinicopathologic risk factors." (PMID 40332222, 2025). "Responsiveness to MAPK pathway inhibitors differs according to the BRAF mutation class and primary tumor type." (PMID 38275886, 2024). "BRAF mutations are recognized as tumor-agnostic driver mutations that play pivotal roles in the pathogenesis of various cancers." (PMID 39040442, 2024). "Due to their high prevalence, mutations in the BRAF proto-oncogene have been tested as potential markers for circulating tumor nucleic acids in patients with TC." (PMID 39336882, 2024). "Our patient population was quite heterogeneous in terms of disease stage and tumor mutational status (except for the subgroup analysis that only consisted of BRAF-mutant patients receiving first-line therapies)." (PMID 39684531, 2024). "Altogether, in vitro results and in vivo subcutaneous experiments confirmed that BRAFV600E PMP tumors are very addicted to BRAF mutation and encorafenib alone was sufficient to exert a potent reduction of cancer cell viability and tumor growth." (PMID 39018564, 2024). "Tumor mutation status was assessed and found to be BRAF wildtype and mutated in the NRAS gene, in Q61R." (PMID 39148899, 2024). "RNF43 mutations have also been associated with aggressive tumor biology, and in BRAF mutated patient derived organoids, RNF43 mutations were recently suggested to have a key role in promoting metastasis in animal models." (PMID 38982444, 2024). "Further studies dissecting the immune response to BRAF-mutated tumours in MSI as well as MSS CRCs, including also analyses of immune checkpoint molecules, are needed to find potential predictive markers for immunotherapy." (PMID 38040818, 2024). "MUC5AC expression is linked to the serrated neoplasia pathway, characterized by CpG island methylator phenotype (CIMP) positivity, BRAF p.V600E mutations, mismatch repair deficiency, and advanced tumor stage." (PMID 39682117, 2024). "Cases were stratified by BRAF V600E mutation status, histology, and a combination of tumor genotype and histology." (PMID 38999527, 2024). "In this study, we showed that habitat-derived radiomic features are superior to conventional metabolic parameters and whole tumor region radiomic features in predicting KRAS/NRAS/BRAF mutations in CRC patients." (PMID 38342905, 2024). "Given these robust responses, the Food and Drug Administration (FDA)–approved dabrafenib/trametinib in June of 2022 for tumor-agnostic use in BRAF-mutated solid tumors." (PMID 39234402, 2024). "The retrospective analysis of the initial tumor identified a BRAF V600E mutation associated with CDKN2A deletion." (PMID 39399174, 2024). "Some of the most common driver mutations found in sporadic CRC are activating mutations in KRAS accounting for 30–40% of all CRCs and activating mutations in BRAF which occur in 5–15 % of the tumours." (PMID 38040818, 2024). "This aligns with the increased biomarker levels and highlights the role of the BRAF mutation in promoting tumor progression and reducing survival." (PMID 39767732, 2024). "Alterations in BRAF occur at a lower frequency in most other tumour types, with the incidence of its mutations estimated to be approximately 1–3% in all cancers." (PMID 38333370, 2024). "MM differs molecularly from CM, showing lower rates of BRAF V600 alterations and tumor mutational burden but a higher rate of chromosomal aberrations." (PMID 38201654, 2024).
tumor (continued). "These inhibitors work by specifically targeting and inhibiting the activity of the mutated BRAF protein, thereby reducing cell proliferation and inducing tumor regression." (PMID 39274556, 2024). "Most importantly, compared with the 5 years AUC values of these established prognostic markers (transcriptomic classification, mutation subtype, tumor stage and BRAF mutant), our signature can achieve higher accuracy value." (PMID 38475660, 2024). "The relationship between age, BRAF mutation status, and tumor aggressiveness is further complicated by the observation that pTERTmut is associated with older age at diagnosis." (PMID 39717106, 2024). "BRAF CNAs showed a significant association with tumor grade, hormone receptors, and molecular subtype." (PMID 38919805, 2024). "Co-occurrence of BRAF V600E mutation and TERT mutations is linked with increased level of tumour aggressiveness in case of PTC as compared to BRAF and TERT mutations occurring alone." (PMID 39558949, 2024). "Seven studies investigated BRAF-mutated circulating tumor nucleic acids (ctNA) as a marker of response to targeted therapy." (PMID 39336882, 2024). "The proportion of KRAS mutated tumours was found to decrease with increasing score of infiltrating cytotoxic T cells, while the proportion of BRAF mutated tumours instead was found to increase." (PMID 38040818, 2024). "We found contrasting associations of immune cell infiltration in KRAS-mutated and BRAF-mutated CRC tumours." (PMID 38040818, 2024). "It has been found that 13% of sporadic colorectal cancer (CRC) show MLH1 hypermethylation, and a BRAF c.1799T>A, p.Val600Glu mutation has often also been identified in tumor DNA." (PMID 39132504, 2024). "Overall, additional exploration is needed to assess potential associations among specific tumor mutations, such as BRAF, EMT, and adenosinergic pathway." (PMID 38388432, 2024). "Elevated preoperative biomarker levels are strongly correlated with advanced tumor stages and poorer survival outcomes, particularly in patients with the BRAF V600E mutation." (PMID 39767732, 2024). "Tumor mutation status was analyzed, resulting into BRAF wildtype and NRAS mutated in Q61X, while expression of PD-1 ligand was < 1%." (PMID 39148899, 2024). "This heterogeneity can result from branch mutations induced by ultraviolet radiation or selective gains of mutant BRAF alleles during early tumor evolution, contributing to differential metastasis and immune evasion." (PMID 39336897, 2024). "In multivariable analysis, adjusting for primary tumor type, Black race was independently associated with increased odds of having a non-V600 BRAF alteration (OR: 1.58; 95% CI 1.13 to 2.20; p < 0.0001)." (PMID 38275886, 2024). "For each 1% increase in BRAF V600E mutation frequency, the risk of tumor invasion, recurrence, and co-occurring gene mutations increases by 10.0%, 8.0%, and 8.8%, respectively." (PMID 38607456, 2024). "It has been also suggested that BRAF V600E mutation is heterogeneously distributed and limited to part of the tumor cells in most PTC samples." (PMID 38540091, 2024). "Targeted therapy focuses on inhibiting tumor growth by targeting specific genetic mutations (e.g., BRAF V600E) to enhance immunotherapy response." (PMID 39336897, 2024). "Treatment received varied depending on RAS/BRAF mutational status and location of the primary tumor." (PMID 39156325, 2024). "An ongoing phase III study (LIBImAb; NCT04776655) aims to assess the superiority of bevacizumab compared to cetuximab with FOLFIRI in mCRC which exhibit RAS/BRAF wt status on tumor tissue, but appear mutated in plasma analysis." (PMID 39682117, 2024). "The deregulation of miR-146b was linked with aggressive behaviour of tumours in clinical PTC specimens positive for BRAF and individuals containing BRAF mutations showed elevated expressions of miR-146b as compared to BRAF wild-type controls." (PMID 39558949, 2024).